HLA-C (major histocompatibility complex, class I, C)
Diseases named in the same sentence as HLA-C in open-access papers (continued):
Sharing a sentence is not in itself a finding about the gene and the disease.
autoimmune disease (continued). "HLA-C, one of the MHC class I heavy chain receptors, modulates the function of NK cells during viral infections, autoimmune diseases, and cancers through the killer cell immunoglobulin-like receptors (KIRs)." (PMID 34895340, 2021). "Combinations of HLA-C with KIR2DS1 and KIR2DS2 have been reported to correlate with the occurrence of autoimmune diseases, leukemia, and inflammatory diseases." (PMID 32184413, 2020). "An ERAP1 risk haplotype may increase the production of an autoantigenic peptide, leading to its presentation by HLA-C*06:02 and the activation of CD8+ T cell, which triggers autoimmune disease." (PMID 38898675, 2024).
melanoma (110 papers, 1993 to 2026). A malignant, usually aggressive tumor composed of atypical, neoplastic melanocytes. "Such alterations in HLA genes, particularly HLA‐C, have been associated with poorer prognosis and resistance to immunotherapy in melanoma and other cancers where immune evasion is critical." (PMID 41017066, 2025). "Here, we report the identification and preclinical characterization of two distinct αβTCRs specific for the melanoma-associated antigen CSPG4 restricted by the highly prevalent HLA-C*07:01 allele (~30%)." (PMID 37849763, 2023). "HLA-A and B alleles of 739 and 709 stage IV melanoma patients were typed serologically; HLA-C (391 stage IV melanoma patients) was typed by PCR." (PMID 16533402, 2006). "We discovered rare T cell populations with specificity for tumor neoepitopes and epitopes from shared tumor-associated antigens in peripheral blood of a melanoma patient including a so far unreported HLA-C*08:02-restricted NY-ESO-1-specific CD8+ T cell population." (PMID 38239352, 2023). "Neither mutation nor gene expression change in JAK1, JAK2, B2M, HLA-A, HLA-B, and HLA-C was observed between pre- and post-treatment tumor samples, which were previously indicated to be associated with resistance to PD-1 antibody treatment in melanoma." (PMID 30872362, 2019). "It significantly decreased the IFN-γ-enhanced expression of HLA-C and immunogenicity of the melanoma cell lines, 1205Lu, WM278, and WM793 for the Vα3S1/Vβ13S1 TCR." (PMID 40243413, 2025). "We cloned the cDNA corresponding to these peptides into plasmids and expressed them for presentation in the HLA-C*06:02+ melanoma cell line WM278." (PMID 41440022, 2025). "Exemplary knockdown of NLRC5 and B2M by siRNA in three different melanoma cell lines confirmed that downregulation of the IFN-γ-induced STAT1 pathway indeed significantly impairs HLA-C expression and Vα3S1/Vβ13S1 TCR stimulation." (PMID 40243413, 2025). "IFN-γ significantly increased HLA-C mRNA levels in primary human melanocytes (PHMs) and melanoma cell lines." (PMID 40243413, 2025). "IFN-γ treatment induced an upregulation of the HLA-class I molecules on PHMs and melanoma cell lines, which was particularly prominent for HLA-C." (PMID 40243413, 2025). "HLA-C*06:02-positive melanoma cell lines can substitute for normal human melanocytes in the analysis of the melanocyte-specific reactivity of the autoreactive Vα3S1/Vβ13S1 TCR." (PMID 40243413, 2025). "Methylation of NLRC5 in melanoma is associated with loss of MHC Class I genes HLA-A, HLA-C and B2M expression, which are linked to immunotherapy resistance and decreased survival." (PMID 40307913, 2025). "Given these encouraging preclinical reports on CSPG4 as an immunotherapeutic target, we set out to further characterize the two previously identified HLA-C*07:01-restricted melanoma reactive T-cell clones 11C/73 and 2C/165 directed against the TAA CSPG4." (PMID 37849763, 2023). "This success prompted us to screen T cells from an HLA-C*08:02-expressing melanoma patient for tumor-antigen reactive T cells with the herein reported HLA-C*08:02 dsSCD that is not available as easYmer." (PMID 38239352, 2023). "In fact, we found that ANGPTL2 mRNA levels were positively correlated with those of HLA‐A, HLA‐B, and HLA‐C in melanoma patients, suggesting that in this cancer context ANGPTL2 signaling does not regulate MHC‐I expression." (PMID 37452654, 2023). "An earlier study reported that HLA-C-bound KIR2DL4 appeared to have protective roles in melanoma, where the KIR2DL3:HLA-C complex appeared to induce NK cell activation; the alternate explanation of spurious allelic variation has yet to be ruled out." (PMID 38067178, 2023). "Among the HLA class I antigens, HLA-C locus recognizes the inhibitory killer cells and suppresses the functions of NK cells in melanoma patients." (PMID 32310824, 2020). "Higher TAP1 (a), HLA-A (b), HLA-B (c) and HLA-C (d) mRNA transcript levels correlated with an increased OS of melanoma patients." (PMID 32825219, 2020).
melanoma (continued). "Downregulation of HLA-C gene expression was the only finding common to all melanoma sEV types (A-375, SKMEL-28, and C-32) evaluated." (PMID 30870978, 2019). "Downregulation of HLA-C mRNA in all three sEV types tested is particularly interesting given that melanoma cells are known to downregulate HLAs to prevent tumor immune surveillance." (PMID 30870978, 2019). "The addition of anti-GD3 mAb only modestly increased the killing activity of already expanded NK cultures from donor HD04 d21H, d21K against HLA-C mismatched melanoma cells (Mel008)." (PMID 23483943, 2013). "In agreement with previous reports, healthy donor NK cells kill various melanoma cells more efficiently in an HLA-C mismatched setup." (PMID 23483943, 2013). "Two representative low passage melanoma cell lines, homozygous either for C1 (Mel008) or for C2 (Mel10), were tested in killing assays in HLA-C -matched or -mismatched settings." (PMID 23483943, 2013). "Co-expression of other inhibitory HLA-A and/or HLA-B with homozygous HLA-C group was similar among melanoma patients and healthy donors." (PMID 23483943, 2013). "Melanoma patients’ sera contain IgG antibodies against HLA-E as well as HLA-B and HLA-C." (PMID 35323192, 2022). "CSPG4 has been previously investigated as an immunotherapeutic target for CAR T cells, among others in melanoma and glioblastoma, and we also observed specific recognition in a panel of CSPG4+/HLA-C*07:01+ melanoma and glioblastoma cell lines." (PMID 37849763, 2023). "In vivo, DNA vaccination led to enhanced antitumor responses against B16F10 melanoma cells and also enhanced responses against a tumor model expressing the KIR2DS2 ligand HLA-C*0102." (PMID 34016721, 2021). "The effect of both high mean HED (calculated as the mean divergence at HLA-A, HLA-B, and HLA-C) and high TMB on OS after ICB has previously been reported to be more pronounced than the effect of either alone in melanoma." (PMID 34732240, 2021). "In agreement with the HLA-C mismatching and KIR-Ligand mismatching models, melanoma cells were more efficiently killed by allogeneic NK cells derived from HLA-C mismatched donors, as compared to the HLA-C matched NK cells." (PMID 23483943, 2013). "Transgenic CD8+ T cells expressing the 11Cαβ- or 2Cαβ-cTCR elicited IFNγ spot formation above background levels when co-cultured with the endogenously HLA-C*07:01+ melanoma cell lines D10, D41, the glioblastoma cell line MZ-257-GBM/HLA-C*07:01 and the lung cancer cell line MZ-LC-16/HLA-C*07:01." (PMID 37849763, 2023). "The HLA-C*07:01 allele is highly prevalent and CSPG4 represents an optimal immunotherapeutic target due to its consistent upregulation in melanoma, and low/absent expression in healthy tissue." (PMID 37849763, 2023). "CSPG4+ melanoma, glioblastoma and lung cancer cell lines were identified and, if negative, retrovirally transduced with HLA-C*07:01." (PMID 37849763, 2023). "This phenomenon was observed regardless of the type of HLA-C group homozygously expressed by the melanoma cells." (PMID 23483943, 2013). "Next, we co-cultured the T-cell clones with either 293T cells transfected with HLA-C*07:01 or HLA-C*07:02 cDNA and loaded with the CSPG4:554-562 (9-mer) or CSPG4:553-562 (10-mer) peptide or cotransfected with CSPG4:1-562 cDNA or co-cultured them with HLA-C*07:02+CSPG4+ melanoma cell lines." (PMID 37849763, 2023). "However, mRNA expression of HLA-C was unaffected in melanoma cells upon NGFR induction, suggesting no interference with NK cell activity." (PMID 36638181, 2023). "PHMs and melanoma cell lines were cultured with or without IFN-γ, exposed to 50 or 100 mJ/cm2 UVB and the expression of HLA-class I molecules (HLA-ABC) and HLA-C analyzed by flow cytometry and fluorescence microscopy." (PMID 40243413, 2025).
viral infections (98 papers, 2004 to 2026). "The inhibitory capacities of HLA-C-reactive KIR are associated with the progression of viral infection." (PMID 39148728, 2024). "Variations of HLA-C and/or KIR alleles have been associated with various disease processes and responses to viral infections, with some studies also reporting an association of specific HLA-C/KIR gene variations with cancer risk." (PMID 38680423, 2024). "On the other hand, in the group of late onset T1D subjects, the significantly more frequent HLA alleles were HLA-B*27 alleles, HLA-C*01:02:01 and C*02:02:02, all known to be associated with increased protection against viral infections." (PMID 39185409, 2024). "An increasing number of studies investigated the impact of KIR/HLA-C interactions on the outcome and progression of viral infections and further explored the underlying mechanisms." (PMID 34831331, 2021). "In summary, to our knowledge, this is the first report to indicate that HLA class I allele mismatches, especially in HLA-C alleles, are significant risk factors for viral infections during the early period following CBT." (PMID 33273656, 2020). "HLA-C has also been associated with many diseases, including viral infections, cancer, autoimmune diseases and transplant failure." (PMID 31921098, 2019). "HLA-C alleles are relatively protected from HLA downregulation following viral infection, and this is likely to be a factor driving the memory inflation observed in our work." (PMID 29312307, 2017). "Moreover, subjects with late-onset had a higher frequency of alleles HLA-B*27 (p-value=0.003), HLA-C*01:02:01 (p-value=0.027) and C*02:02:02 (p-value=0.01), known to be associated with increased protection against viral infections." (PMID 39185409, 2024). "During the 2020 outbreak caused by the severe acute respiratory syndrome coronavirus 2 (SARS-CoV2), polymorphisms in HLA-C were correlated with a higher mortality rate due to viral infection by triggering an overactive immune response SWED4Wlinked to the KIR mechanism of NK cells." (PMID 37465164, 2023). "Our findings suggest that appropriate graft selection as well as prophylaxis and early intervention for viral infection in such high-risk patients with ≥ 3 HLA class I allele-level mismatches, including HLA-C, may improve CBT outcomes." (PMID 33273656, 2020). "HLA-C affects viral infections and is implicated in several human autoimmune diseases." (PMID 32184413, 2020). "For example, if the individual possesses rare HLA-A allotype but dominant HLA-B or C allotypes, the HLA-B or HLA-C restricted epitopes also can elicit robust T-cell immunity to defend against viral infection." (PMID 40469303, 2025). "Certain KIR receptors, like KIR2DL1 and KIR2DS1, recognize HLA-C molecules, which can influence NK cell activation or inhibition and, consequently, the immune response to viral infections." (PMID 39599823, 2024). "Although expressed on the cell surface about ten times lower than HLA-A and B, HLA-C represents a potentially particular target for the mechanisms put in place by viral infections, acting as a ligand for both T cell receptors and NK cell receptors." (PMID 36816025, 2023). "These evolutionary characteristics conferring to HLA-C locus particular efficacy in exerting immuno pressure on viral infection, have probably made it a preferential target by viral mechanisms." (PMID 36325330, 2022). "The HLA-C mediated protection, harnessing NK cells, is relevant to a number of viral infections, including SARS‐CoV‐1 infection." (PMID 35185875, 2022). "Among the main findings of this study, whole blood DNA methylation alteration was observed in genes, including HLA class I C (HLA-C), mainly involved in the response of interferon to viral infection." (PMID 36325330, 2022). "HLA-C has been widely studied for its pivotal role in the immune cellular response to viral infections." (PMID 36499177, 2022).
viral infections (continued). "Several studies have shown that KIR and HLA-C genes influence the immune response to viral infections, but few studies have examined the role of KIR and HLA-C in malaria infection, and these have used low-resolution genotyping." (PMID 33632228, 2021). "The following chapter briefly summarizes the information about KIRs and HLA-C in the context of other viral infections." (PMID 34831331, 2021). "In this review, we focus on the unique role of HLA-C in regulating NK cell functions and its consequences in the setting of viral infections." (PMID 34831331, 2021). "HLA-C mismatches in graft-versus-host direction showed a significantly higher incidence of viral infection (hazard ratio (HR), 3.67; p = 0.01), while mismatches in HLA-A, -B, or -DRB1 were not significant." (PMID 33273656, 2020). "We investigated the impact of viral infections and vaccination on frequencies of HLA-C*03:04/peptide-binding KIR2DL2/3+ NK cell populations and their function." (PMID 30386333, 2018). "Since all the data indicate that HLA-C forms at least part of the KIR2DS1 ligand the question that arises is how does HLA-C differ upon viral infection such that KIR2DS1 is brought into play?" (PMID 28424684, 2017). "Blockade of inhibitory KIR interaction with HLA-C has been pursued as therapeutic strategy in malignancy and viral infection." (PMID 26809736, 2016). "HLA-C is unique among the classical MHC class I molecules for its role in the control of viral infections and recognition of abnormal or missing self." (PMID 25083782, 2014). "HLA-C is unique among the classical MHC class I molecules for its role in the control of viral infections and recognition of abnormal or missing self, by presenting antigens to cytotoxic T lymphocytes (CTL) and providing an inhibitory signal to NK cells." (PMID 25083782, 2014). "Prompted by observations of HSCT, responses to viral infections, and success in pregnancy, it is now appreciated that HLA-C reactive KIR play a critical role in NK cell function, but must be examined in the context of their ligands." (PMID 23189078, 2012). "HLA-C molecules are expressed in lower quantities at the cell surface, compared with HLA-A and -B and, therefore, often receive less attention in studies of responses to viral infection." (PMID 39337964, 2024). "Moreover, HLA-Cw*03-restricted CD8+T cells have been shown to induce escape mutations in HIV as a result of immune pressure, demonstrating that HLA-C-restricted T cells are involved in defence against viral infections." (PMID 36816025, 2023). "Given the impact of KIR/HLA-C interactions on the acquisition and progression of viral infections, this review sought to glean and discuss information on the unique role of HLA-C in regulating the immune responses of NK cells in the course of viral infections." (PMID 34831331, 2021). "In addition to HIV-1, HCV and CMV infection, there are only a few reports about the role of HLA-C in other viral infections." (PMID 34831331, 2021). "These factors, including selection bias of donor grafts and genetic linkage of HLA class I genes, support the findings that HLA-C mismatches are the most powerful predictive factors for the higher incidence of viral infections among the other HLA class I genes." (PMID 33273656, 2020). "Regulation of HLA-C cell surface expression depends on transcriptional as well as post-transcriptional regulatory mechanisms and the resulting HLA-C cell surface expression levels were shown to impact CD8+ effector T cell (Teff) responses to viral infection as well as allogeneic Teff responses." (PMID 31921098, 2019). "In conclusion, the findings in this study demonstrate consistent hierarchies in the frequencies of KIR2DL2/3+ NK cells binding HLA-C*03:04/peptide complexes that were not changed by an underlying viral infection or vaccination." (PMID 30386333, 2018).
viral infections (continued). "An extension of this argument might be that persistent viral infections have served to act as an important selective pressure for the evolution of HLA-C to maintain lifelong viral control." (PMID 29312307, 2017). "For these reasons, the HLA-C levels are finely tuned during viral infections." (PMID 23841087, 2013). "On the contrary, the presence of C2 alleles (HLA-CLys80) such as HLA-C*07:01 and -C*06:02, which are ligands for the inhibitory KIR2DL1 and activating KIR2DS1, would theoretically lead to lower NK inhibition and higher activation would be more beneficial for the clearance of viral infections." (PMID 35960731, 2022). "However, high HLA-C expression levels could damage viral infections due to the increase of the antigen presentation to CTL." (PMID 23841087, 2013). "The sGenes found within this gene set include MX1, HLA-C, and IFI44, which play important roles in host response specifically to viral infections." (PMID 41542048, 2026). "NK cells are crucial for the early control of viral infections and accumulating evidence indicates that interactions between HLA-C and its respective KIR receptors determine the outcome and progression of viral infections." (PMID 34831331, 2021). "Thus, HLA-C might be important in the immune response to the viral infection." (PMID 33273656, 2020). "The CXCL10/11high basal cells also had upregulated mRNA encoding for complement components (C1R and C1S), MHC class I (HLA-A, HLA-B, HLA-C, and B2M), and metalloproteases MMP2 and MMP13, the latter reducing repair during viral infection in bronchial epithelial cells." (PMID 40980495, 2025). "The combination of KIR genes with HLA-C genotypes was also analyzed in male AC patients with and without viral infections and healthy controls." (PMID 38397937, 2024). "These susceptibility or innate immunity mechanisms to viral infections are due to the interaction of HLA-C and its variants with KIR of NK cells and the not-so-specific interaction of HLA-C and its variants with cytotoxic T lymphocytes." (PMID 37465164, 2023). "HLA-C is also a ligand for killer immunoglobulin receptors (KIRs) expressed on natural killer (NK) cells, which survey MHC class I levels on cell surfaces and can induce cell death when levels decrease during cell stress or viral infection." (PMID 35606880, 2022). "KIR2DL2/3 bind to HLA-C molecules, but the modulation of these interactions by viral infections and presentation of viral epitopes is not well-understood." (PMID 30386333, 2018). "Individuals with HLA-C*04:01 and HLA-C*12:03 haplotypes, in combination with certain types of HLA-A and HLA-B, could have partial protection or resistance to HIV by triggering an additive immune effect that better controls viral infection." (PMID 37465164, 2023). "Since NK cells have been shown to limit the magnitude of the anti-viral T-and B-cell responses, the outcome of viral infections, especially the degree to which NK cells kill activated CD4 cells, could be modulated by variation in the endogenous HLA-C levels mediated by the NK-Pro." (PMID 32219494, 2020). "HLA-C tetramers have been previously reported to bind to primary human NK cells, but it remains unknown whether the frequencies of HLA-C tetramer-binding KIR2DL2/3+ NK cells change during viral infections or are influenced by antigen-exposure." (PMID 30386333, 2018). "Thus, we suggest that the paucity of strong HLA-C restricted CD8+ T cell responses, at least in an acute viral infection like yellow fever virus, is not due to HLA-C having been neglected in the scientific literature, but rather reflects a true biological phenomenon." (PMID 32983097, 2020).